NLRP1 (NLR family pyrin domain containing 1)
Diseases named in the same sentence as NLRP1 in open-access papers (continued):
Sharing a sentence is not in itself a finding about the gene and the disease.
dermatitis (2 papers, 2020 to 2025). An inflammatory process affecting the skin. "In addition, unraveling the critical mechanism of action engaged allowed determining ZAKα kinase and NLRP1 as critical pharmacological targets that support PortimineA-driven skin inflammation." (PMID 39948420, 2025). "In conclusion, we clarify that PM2.5 activates NLRP1 via ROS/NF-κB signaling in HaCaT cells, which suggests that PM2.5 may induce dermatitis or increase the risk of other skin diseases through the inflammasome pathway." (PMID 32922182, 2020). "In consideration of NF-κB pathway was closely related to the activation of NLRP1 and NLRP3 inflammasomes in neurons 24, we further investigated whether NF-κB would also play a role in skin inflammation." (PMID 32922182, 2020).
diabetic kidney disease (2 papers, 2021 to 2025). Progressive kidney disorder caused by vascular damage to the glomerular capillaries, in patients with diabetes mellitus. "Soares and colleagues demonstrated that NLRP1 gain-of-function variants protect against diabetic kidney disease in humans, highlighting an emerging protective role of NLRP1 against metabolic stress." (PMID 40433411, 2025). "Diabetic kidney disease (DKD) T1D patients with rs2670660 and rs11651270 NLRP1 polymorphisms (gain‐of‐function variants) were associated with having a decreased risk of developing DKD." (PMID 33682108, 2021).
endothelial dysfunction (2 papers, 2021 to 2022). In vascular diseases, endothelial dysfunction is a systemic pathological state of the endothelium (the inner lining of blood vessels) and can be broadly defined as an imbalance between vasodilating and vasoconstricting substances produced by (or acting on) the endothelium. "NLRP3 and NLRP1 are involved in endothelial dysfunction through the regulation of immune–inflammatory processes in arterial endothelial cells." (PMID 36014040, 2022). "NLRP3 and NLRP1 are responsible for endothelial dysfunction through the regulation of immune–inflammatory processes in arterial endothelial cells." (PMID 36014040, 2022). "Finally, it must be stressed that inflammasomes other than NLRP3, such as AIM2, NLRP1, NLRC4, and NLRP6, have not been thoroughly investigated so far in the context of the development of endothelial dysfunction and the impact on pathogenesis and progression of T2DM." (PMID 33546399, 2021).
familial Mediterranean fever (2 papers, 2023 to 2024). Familial Mediterranean fever (FMF) is an autoinflammatory disorder characterized by recurrent short episodes of fever and serositis resulting in pain in the abdomen, chest, joints and muscles. "In familial Mediterranean fever, pyrin has been shown to function also as an autophagy receptor that targets the inflammasome components NLRP3, NLRP1, and caspase-1 for degradation." (PMID 38593810, 2024).
glioblastoma (2 papers, 2022 to 2025). The most malignant astrocytic tumor (WHO grade IV). "Only NLRP1 in OV, CASP8 in pheochromocytoma/paraganglioma (PCPG), glioblastoma (GBM), etc., showed a positive correlation between methylation and gene expression (P<0.05)." (PMID 35795676, 2022).
hyperlipidemia (2 papers, 2023 to 2024). "Afteradding the variables into the multivariate logistic analysis, the resultsindicated that age, BMI, smoking, DM, hyperlipidemia, NLRP1 and ALP wereindependent risk factors for CAC in patients with CAD." (PMID 39139411, 2024). "Second, we proposed andvalidated a valuable prediction model, embracing an extensive set of clinicalrisk factors that are easily accessible, such as age, smoking, DM,hyperlipidemia, ALP and TG, and incorporating the serum NLRP1 level." (PMID 39139411, 2024).
lung diseases (2 papers, 2022 to 2025). "Studies on NLRP1 have predominantly concentrated on nonneoplastic lung diseases." (PMID 40026444, 2025).
lymph node metastasis (2 papers, 2017 to 2022). "Chi-squared analysis showed NLRP1 expression to be associated with lymph node metastasis (p = 0.003), TNM stage (p = 0.003), and Ki-67 detection (p < 0.001)." (PMID 29214170, 2017). "Furthermore, correlation analysis of NLRP1/NLRP3 with clinical features showed that high expression of NLRP1/NLRP3 correlated significantly with worse prognosis in GC patients with lymph node metastasis." (PMID 36541912, 2022).
malaria (2 papers, 2021 to 2025). Malaria is a serious and sometimes fatal disease caused by a parasite that commonly infects a certain type of mosquito which feeds on humans. "Our study identifies a genetic variant underlying NLRP1 contribution to GM and suggests that NLRP1 may be an under-explored inflammasome receptor in malaria and infected erythrocytes' sensing." (PMID 40923647, 2025). "Although a role for NLRP1 in the pathogenesis of malaria has not yet been determined, one study of genetic polymorphisms suggests that SNPs (rs1215022, rs2670660, and rs11651270) in the NLRP1 gene are associated with malaria severity in Brazilian Amazonian patients with P. vivax." (PMID 33672278, 2021).
metabolic dysfunction-associated steatotic liver disease (2 papers, 2022 to 2026). Metabolic dysfunction-associated steatotic liver disease (MASLD, formerly known as nonalcoholic fatty liver disease or NAFLD) is a type of liver disease that is not caused by alcohol. "For instance, the NLRP1-IL-18 pathway was shown to promote the generation of mature MDSCs in multiple myeloma, and the Nlrc4 inflammasome in controlling CRC metastasis to the liver in non-alcoholic fatty liver disease (NAFLD)." (PMID 35517498, 2022).
migraine (2 papers, 2017 to 2021). "For instance, a recent genome-wide association analysis (GWAS) that compared genetic data of 59,674 migraine cases and 316,078 control individuals yielded 38 genomic susceptibility loci in human, among which 5 genes, i.e. TSPAN2, MEF2D, NLRP1, JAM3 and NOTCH4, that are associated with inflammation." (PMID 34112082, 2021). "Interestingly, one of the novel migraine-associated SNPs included in our GRS, rs75213074, is located near NLRP1, which encodes for the sensor component of an inflammasome (a protein complex that activates caspases and cytokines in response to damage-associated signals)." (PMID 28656458, 2017). "Also the roles of NLRP1, NLRP2 and AIM2 inflammasome complexes needs further study in migraine and its comorbid diseases." (PMID 34112082, 2021). "However, there is no data implying a relation between NLRP1 or NLRP2 inflammasome and migraine and/or CSD." (PMID 34112082, 2021).
multiple myeloma (2 papers, 2022 to 2023). "The NLRP1 inflammasome has also been studied in the TME of multiple myeloma, where NLRP1 increases the production of MDSCs by sensing disturbances in hematopoietic stress or cellular homeostasis and responding by secreting IL-18, which leads to accelerated tumor progression." (PMID 37497237, 2023).
pancreatic adenocarcinoma (2 papers, 2024 to 2025). "Conversely, in the case of pancreatic adenocarcinoma, we observed a substantial increase in NLRP1 protein level within primary tumors when compared to normal samples." (PMID 40237399, 2025).
Parkinson disease (2 papers, 2024). A progressive degenerative disorder of the central nervous system characterized by loss of dopamine producing neurons in the substantia nigra and the presence of Lewy bodies in the substantia nigra and locus coeruleus. "The DisGeNET database labels NLRP1, MSC, PTK2B, TAC1 and FOSL2 as genes associated with Parkinson’s disease, with association scores of 0.964, 0.944, 0.907, 0.889 and 0.888, respectively." (PMID 38350848, 2024).
pneumococcal meningitis (2 papers, 2017 to 2019). An acute purulent infection of the meninges and subarachnoid space caused by Streptococcus pneumoniae, most prevalent in children and adults over the age of 60. "A study including 531 adult pneumococcal meningitis patients and 376 controls studied two polymorphisms in CARD8 and NLRP1 both coding for proteins required for activation of NFκB or caspases in the context for inflammation or apoptosis respectively." (PMID 31519222, 2019).
pustular psoriasis (2 papers, 2018 to 2022). "Therefore, IL-36RN-associated GPP, and CARD14-mediated pustular psoriasis, PRP type V and familial keratosis lichenoides chronica (KLC) caused by NLRP1 mutation, can be considered AIKDs." (PMID 30386326, 2018).
Sézary syndrome (2 papers, 2023 to 2024). "Despite these abnormal patterns of expression, NLRP3 and AIM2 were equally expressed in the different groups, while NLRP1 expression was observed in Sézary syndrome skin compared to controls." (PMID 38397043, 2024). "Herein, to verify whether the expression of inflammasome components could be altered by Sézary syndrome, we assessed the expression of NLRP1, NLRP3, AIM2, IL-1B and IL-18 by immunohistochemistry in the epidermal and dermal layers of skin from SS patients." (PMID 36902104, 2023).
subarachnoid hemorrhage (2 papers, 2022 to 2023). A serious neurological disorder characterized by intracranial hemorrhage into the subarachnoid space. "Current studies have shown that a variety of inflammasomes are involved in the process of neuronal cell pyroptosis, such as AIM2, NLRP1, and NLRP3, after subarachnoid hemorrhage, among which NLRP3 is the best studied." (PMID 38044382, 2023).
unstable angina (2 papers, 2023 to 2025). "The present study expands on previous findings demonstrating an association between NLRP1 and the severity of coronary artery lesions in patients with unstable angina." (PMID 41189992, 2025). "Through binary logistic regression analysis, we found that NLRP1 is an independent risk factor for the occurrence of unstable angina." (PMID 37214347, 2023).
abortion (1 paper, 2021). the ending of pregnancy by removing a fetus or embryo before it can survive outside the uterus. "By investigating rat abortion model, the results showed NLRP1 and NLRP3 expression in abortion rat uterus increased (∗P < 0.05, ∗∗P < 0.01), TFR1 and ACSL4 expression increased and GPX4 expression was decreased (∗P < 0.05, ∗∗P < 0.01), that compared with the control group." (PMID 34490257, 2021). "In our previous work, we found that the NLRP1 inflammasome was overexpressed in an oxidative stress model in placental trophoblast cells and in the rat model of abortion that these could be used to investigate the presence of ferroptosis in an oxidative stress model." (PMID 34490257, 2021).
acute angle closure glaucoma (1 paper, 2023). "NLRP1 also plays an important role in nervous system diseases and is involved in the pathogenesis of acute angle closure glaucoma." (PMID 37214347, 2023).
acute leukemia (1 paper, 2023). A clonal (malignant) hematopoietic disorder with an acute onset, affecting the bone marrow and the peripheral blood. "Since patients with acute leukemia have an increased risk of developing infections, both because of leukemia and because of its treatment, further studies are necessary to evaluate the role of NLRP1 rs12150220 in order to be able to predict the risk of infections in ALL." (PMID 37577033, 2023).
acute lymphoblastic leukemia (1 paper, 2021). Leukemia with an acute onset, characterized by the presence of lymphoblasts in the bone marrow and the peripheral blood. "In addition, the variant NLRP1 A/T rs12150220 can promove protection from infectious diseases in acute lymphoblastic leukemia patients." (PMID 33972620, 2021).
aging (1 paper, 2011). A developmental process that is a deterioration and loss of function over time. "However, our data suggest that therapeutic intervention with probenecid alone or another agent that inhibits the NLRP1 inflammasome, with corresponding reduction in proinflammatory cytokines, may improve overall cognitive outcomes and reduce symptoms of normal cognitive aging." (PMID 22133203, 2011).
anthrax (1 paper, 2022). "The only well‐known trigger of NLRP1 activation is anthrax lethal toxin excreted by anthracis, and NLRP1 activation can defence against anthracis infection via inducing pyroptosis." (PMID 35415891, 2022).
Arrhythmia (1 paper, 2023). Any cardiac rhythm other than the normal sinus rhythm. "We investigated the clinical significance of NLRP1 expression in patients with STEMI complicated with arrhythmia." (PMID 37492291, 2023). "The NLRP1 pathway is associated with the presence of arrhythmias after PCI treatments, and the NLRP1 expression level may be useful as a predictor of arrhythmia in patients with STEMI." (PMID 37492291, 2023). "The NLRP1 pathway is active during the process of arrhythmias after PCI treatments and the NLRP1 level may be used as a predictor of arrhythmias after PCI in patients with STEMI." (PMID 37492291, 2023).
Behcet disease (1 paper, 2016). A chronic, relapsing, multisystemic vasculitis characterized by mucocutaneous lesions, as well as articular, vascular, ocular and central nervous system manifestations. "This study aimed to investigate whether single nucleotide polymorphisms (SNPs) of five NLR family genes (NOD1, NOD2, NLRP1, NLRP3 and CIITA) are associated with Behcet’s disease (BD) in a Chinese Han population." (PMID 26833430, 2016).
Burkholderia Infections (1 paper, 2021). Infections with bacteria of the genus BURKHOLDERIA. "It is possible that Burkholderia infection triggers stress that activates NLRP1 inflammasome activation, leading to ASC and CASP1 activation, although the participation of other inflammasomes such as the non-canonical caspase-4 could not be ruled out." (PMID 34821529, 2021).
cardiomyopathy (1 paper, 2023). A disease of the heart muscle or myocardium proper. "Change of NLRP1 and CASP1 has also been demonstrated to be associated with cardiomyopathy." (PMID 37724419, 2023).
chronic kidney disease (1 paper, 2017). Impairment of the renal function secondary to chronic kidney damage persisting for three or more months. "Among the NLR family members (NLRP1, NLRP2, NLRP3, NLRP6, NLRP12, and NLRC4), NLRP3 deficient mice had less tubular injury, inflammation, and renal fibrosis in chronic kidney disease (CKD)." (PMID 29100270, 2017).
complex regional pain syndrome (1 paper, 2021). A chronic pain syndrome characterized by a disproportionate spontaneous or stimulus-induced pain, accompanied by a variably mixed myriad of autonomic and motor disorders including symptoms such as swelling, allodynia, skin blood supply and trophic disturbances. "NLRP1 (NALP1) has been associated with different pain syndromes, including neuropathic pain, complex regional pain syndrome, adjuvant arthritis, chronic pelvic pain syndrome and may serve as a new target for pain therapy." (PMID 34112082, 2021).
coronary artery calcification (1 paper, 2025). Calcification of the coronary artery, used as a measure of coronary atherosclerosis, a risk factor for myocardial infarction. "A recent study also revealed that serum NLRP1 levels independently predict coronary artery calcification." (PMID 40124544, 2025).
cryopyrin-associated periodic syndrome (1 paper, 2020). Cryopyrin associated periodic syndrome (CAPS) defines a group of autoinflammatory diseases, characterized by recurrent episodes of systemic inflammatory attacks in the absence of infection or autoimmune disease. "The prevalence of organ-specific phenotypes (e.g., cutaneous phenotypes in NLRP1-associated syndromes) or cytokine-driven diseases (IL-18 in NLRC4-associated syndromes compared to IL-1 in NLRP3/Cryopyrin-Associated periodic Syndromes) may be largely due to differential transcriptional regulations." (PMID 33138274, 2020).
cutaneous leishmaniasis (1 paper, 2024). Leishmaniasis affecting the skin. "NLRP1 transcripts were reported to be upregulated in skin biopsies of human cutaneous leishmaniasis lesions." (PMID 39250503, 2024). "In addition to NLRP3, higher transcript levels of AIM-2 and NLRP1 have been reported in localized skin lesions of patients with cutaneous leishmaniasis due to L. braziliensis and L. amazonensis." (PMID 39250503, 2024).
cutaneous lupus erythematosus (1 paper, 2024). An autoimmune disorder that manifests as different lupus-specific skin disorders; it can occur with systemic lupus erythematosus, or as a singular disease. "This study also showed that NLRP1, NLRP3, and ASC were all expressed in the skin of patients that had cutaneous lupus erythematosus as well as in the normal control patients at a lower level." (PMID 39026932, 2024).
cystic fibrosis (1 paper, 2023). Autosomal recessive disorder caused by pathogenic variants in the CFTR gene (cystic fibrosis transmembrane conductance regulator), which encodes a chloride and bicarbonate channel expressed in epithelial cells, and follow the diagnosis criteria. "Here, Pinilla and colleagues address the ability of the human NLRP1 inflammasome-forming sensor to detect translation inactivation by bacterial toxins in healthy and cystic fibrosis airway and corneal epithelial cells." (PMID 37642996, 2023). "Finally, cystic fibrosis cells from patients exhibit exacerbated P38 activity and hypersensitivity to EXOA-induced ribotoxic stress–dependent NLRP1 inflammasome activation, a process inhibited by the use of ZAKα inhibitors." (PMID 37642996, 2023).
dengue (1 paper, 2019). "Moreover, a decrease in the expression of the inflammasome-related genes NLRP1, NLRC4, caspase-1, IL-1β and IL-18 was observed, as well as an increase in serum levels of C-reactive protein and IL-10 in dengue patients versus healthy donors." (PMID 30901375, 2019).
Dry skin (1 paper, 2020). Skin characterized by the lack of natural or normal moisture. "The present study demonstrated that NLRP1 inflammasome-mediated inflammatory signal contributes to dry skin-induced chronic itch by TRPV1 channel and plays an important role in itch transduction, and it also connects age and gender to chronic itch." (PMID 32312281, 2020). "In this study, we demonstrated that spinal cord NLRP1 inflammasome-mediated inflammatory processes contribute to dry skin-induced chronic itch by activating TRPV1 channel and plays an integral role in itch transduction." (PMID 32312281, 2020). "Combined with our above results, we speculate that NLRP1 inflammasome could contribute to the upregulation of TRPV1 in dry skin induced chronic itch model." (PMID 32312281, 2020). "However, little is known about the role of NLRP1 inflammasome in dry skin-induced chronic itch." (PMID 32312281, 2020).
enterovirus infection (1 paper, 2021). "NLRP1 and NLRP3 have distinct expression patterns including in epithelial cells, which are important targets of enterovirus infection." (PMID 33410748, 2021).
eosinophilia (1 paper, 2021). "Given that insufficient NLRP1 exacerbated eosinophilia and IL-13 levels in the mouse model we studied, it is conceivable that blocking this axis with agents such as IL-4Rα may work more effectively in carriers of the NLRP1 M1184V variant." (PMID 33378691, 2021). "In addition, in vivo data from a mouse model of airway inflammation reveal a protective role for NLRP1 inflammasome activation reducing eosinophilia in this setting." (PMID 33378691, 2021).
Erythema (1 paper, 2022). Redness of the skin, caused by hyperemia of the capillaries in the lower layers of the skin. "SLE has a strong genetic background; two genetic association studies revealed that variations in IL-1β and NLRP1 are associated with SLE-related erythema in Brazilian cohorts." (PMID 35664004, 2022). "For example, an NLRP1 inflammasome inhibitor may be effective in patients with LN complicated by arthritis or erythema; an NLRP3 inflammasome inhibitor may be more effective in LN patients with NP-SLE." (PMID 35664004, 2022).
Glucose intolerance (1 paper, 2018). Glucose intolerance (GI) can be defined as dysglycemia that comprises both prediabetes and diabetes. "Murine studies have documented how the deletion of NLRP1 results in an obese phenotype with increased lipid accumulation and glucose intolerance, and that the NLRP1 deficient phenotype is exacerbated further when animals are placed on a high fat diet." (PMID 29515457, 2018).